SPINT1 (serine peptidase inhibitor, Kunitz type 1)
Description:
Inhibitor of HGFAC. Inhibits serine protease activity of ST14/matriptase in vitro. Inhibits serine protease activity of TMPRSS13, via the BPTI/Kunitz inhibitor 1 domain.
Synonyms: HAI-1; HAI1; HAI; MANSC2
Tractability: Antibody: UniProt places it where antibodies can reach, with high confidence; its Gene Ontology location is reachable by antibodies, with high confidence; UniProt predicts a signal peptide or a membrane-spanning region; the Human Protein Atlas places it where antibodies can reach. PROTAC: ubiquitination databases record sites on it; its protein half-life has been measured.
Gene: Protein-coding gene on chromosome 15 (40,843,513 to 40,858,383, forward strand). Ensembl gene ENSG00000166145.
Subcellular location: Secreted; Cytoplasm; Cell membrane
Subcellular location (Human Protein Atlas): Cytosol; Plasma membrane; Nucleoplasm; Predicted to be secreted
Pathways (Reactome):
Signal Transduction: MET Receptor Activation; Signaling by MST1
Gene Ontology:
Molecular function: protein binding; serine-type endopeptidase inhibitor activity
Biological process: epidermis development; epithelium development; extracellular matrix organization; cellular response to BMP stimulus; negative regulation of neural precursor cell proliferation; positive regulation of glial cell differentiation
Cellular component: cytoplasm; cytosol; extracellular exosome; extracellular region; plasma membrane; membrane
Genetic constraint (gnomAD): Loss-of-function variants: 38 observed, 56 expected, observed/expected ratio (o/e) 0.68, 90% interval 0.52 to 0.89. The upper end of that interval is the gene's LOEUF score, 0.89, which puts it in group 3 of 6, group 1 being the genes least tolerant of losing a copy. Missense variants: 644 observed, 723.04 expected, observed/expected ratio (o/e) 0.89, 90% interval 0.83 to 0.95. Synonymous variants: 283 observed, 294.26 expected, observed/expected ratio (o/e) 0.96, 90% interval 0.87 to 1.06.
Homologues: Orthologues: chimpanzee SPINT1 (99% identical), macaque SPINT1 (92% identical), dog SPINT1 (83% identical), rabbit SPINT1 (80% identical), pig SPINT1 (80% identical), mouse Spint1 (80% identical), guinea pig SPINT1 (79% identical), rat Spint1 (76% identical), tropical clawed frog spint1 (46% identical), zebrafish spint1b (37% identical), zebrafish spint1a (36% identical), zebrafish lrp11 (18% identical), and 11 more. Paralogues in human: LRP11 (21% identical), SPINT2 (16% identical), KIAA0319L (15% identical), KIAA0319 (15% identical), TFPI2 (13% identical), AMBP (13% identical), TFPI (13% identical), WFIKKN1 (13% identical), WFIKKN2 (13% identical), WFDC8 (10% identical), EPPIN (7% identical), SPINT4 (5% identical), and 1 more.
Diseases named in the same sentence as SPINT1 in open-access papers:
SPINT1 is named in the same sentence as 77 diseases in open-access papers, as found by Europe PMC text mining. Sharing a sentence is not in itself a finding about the gene and the disease. The quoted sentences say what the papers report.
breast carcinoma (18 papers, 2012 to 2025). "To unveil the mutation distributions of SPINT1/2 in breast carcinoma, we searched COSMIC database." (PMID 34381422, 2021). "The assays confirmed that CREB3L1, CAPG, and SPINT1 were significantly upregulated in breast cancer group, while GRK3 was significantly downregulated when compared to normal group, respectively." (PMID 39015775, 2024). "SPINT1/2 expression was upregulated in breast cancer, and was relatively higher in human epidermal growth factor receptor 2 (HER2) and node positive patients." (PMID 34381422, 2021). "The correlation between SPINT1 expression and prognosis in breast cancer patients with different clinicopathological parameters." (PMID 34381422, 2021). "Mutations in protein-encoding genes induce expression changes in cancer, therefore, we investigated the genetic alteration of SPINT1/2 in breast cancer with the cBioportal database." (PMID 34381422, 2021). "Our study identified the expression profiles, prognostic significance and potential roles of SPINT1/2 in breast carcinoma." (PMID 34381422, 2021). "To further evaluate SPINT1/2 protein expression in normal versus breast cancer tissues, we explored the HPA database." (PMID 34381422, 2021). "In our study, multiple databases and bioinformatics tools were used to investigate SPINT1/2 expression profiles, prognostic significance, genetic alteration, methylation, and regulatory network in breast carcinoma." (PMID 34381422, 2021). "First, we analyzed SPINT1/2 mRNA expression in normal and breast cancer tissues using the Oncomine database." (PMID 34381422, 2021). "Next, we used MethSurv to identify which methylation sites in SPINT1/2 were significantly correlated with breast cancer prognosis." (PMID 34381422, 2021). "This study aimed to investigate the expression and roles of SPINT1/2 in breast cancer using bioinformatics approaches." (PMID 34381422, 2021). "By analyzing all 13 methylation sites of SPINT1 in breast cancer patients, we found three hypomethylated sites (TSS200; 5’-UTR-cg11701759, 3’-UTR-Open_Sea-cg04519327, and TSS200; 5’-UTR-Island-cg27510007) were significantly correlated with a poorer OS." (PMID 34381422, 2021). "These study results showed that the SPINT1/2 were potential prognostic biomarker for patients with breast cancer." (PMID 34381422, 2021). "The results showed that 3,499 genes (red dots) were positively and 6,420 genes (green dots) were negatively correlated with SPINT1 in breast cancer (FDR <0.01)." (PMID 34381422, 2021). "The results showed that SPINT1/2 methylation was negatively correlated with its expression in breast cancer." (PMID 34381422, 2021). "A recent study found that macrophage-derived HIF-2α regulates the expression of the serine protease inhibitor Kunitz type 1 (SPINT1), which contributes to the tumor-suppressive functions of TAMs in breast cancer development." (PMID 34603327, 2021). "We further investigated the prognostic correlations of SPINT1/2 in breast cancer using the PrognoScan database." (PMID 34381422, 2021). "We explored the bc-GenExMiner v4.5 for the relationship between SPINT1/2 expression and molecular subtypes of breast cancer." (PMID 34381422, 2021). "These four variables were also selected in the breast cancer mortality model, in addition to ANGPTL4, a VEGF-13 marker implicated in angiogenesis, and SPINT1, a claudin-low feature involved in epithelial cell differentiation." (PMID 31542876, 2020). "Moreover, analysis of the RNA-Seq data of 1,222 TCGA breast cancer samples showed that SPINT1/2 were overexpressed in non- and paired cancer tissues compared to normal controls." (PMID 34381422, 2021). "In breast carcinoma, SPINT1/2 were reciprocally correlated and shared common co-expressed genes." (PMID 34381422, 2021). "We found that SPINT1/2 expression was significantly correlated with prognosis in breast cancer." (PMID 34381422, 2021).
breast carcinoma (continued). "Targeting SPINT1 may be a promising strategy for breast cancer patients, particularly for the HER2+ subgroup." (PMID 34381422, 2021). "Additionally, SPINT1 methylation is decreased in breast cancer, representing the same status as in hepatocellular carcinoma." (PMID 34381422, 2021). "Moreover, several hypomethylated sites in the SPINT1/2 genes correlated with patient prognosis have also been identified, representing ideal aberrantly demethylated sites of SPINT1/2 in breast cancer." (PMID 34381422, 2021). "Therefore, SPINT1/2 were theoretically supposed to be downregulated in breast carcinoma." (PMID 34381422, 2021). "We discovered that SPINT1 and SPINT2 have different roles and overlapping functions in breast cancer biology." (PMID 34381422, 2021). "SPINT1 and SPINT2 expression were reciprocally correlated in breast cancer, which was in accordance with reports that they were frequently co-expressed in the same cell." (PMID 34381422, 2021). "Although most studies involving SPINT1 or SPINT2 reported reduced expression in cancers, we observed a paradoxical upregulated expression of SPINT1/2 in breast cancer." (PMID 34381422, 2021). "As SPINT1/2 mRNA expression were found to be upregulated in HER2+ breast cancer, we further appraised their protein level in 21 breast cancer specimens via IHC." (PMID 34381422, 2021). "Currently, there are few studies on the expression and functions of SPINT1 and SPINT2 in breast cancer." (PMID 34381422, 2021). "All these results indicated that SPINT1 and SPINT2 jointly regulated cell attachment and metastasis in breast cancer." (PMID 34381422, 2021). "Results showed one out of 45 datasets for SPINT1 and 12 out of 53 analyzes for SPINT2 reported mRNA upregulation in breast cancer tissues." (PMID 34381422, 2021). "ST14/Prss14 is one of such genes: its expression was low in ERlow breast cancer cell lines, clustered together with CDH1 and its two inhibitors, SPINT1 and SPINT2." (PMID 27167193, 2016). "CREB3L1, CAPG, SPINT1, and GRK3 might be suitable for clinical application in early breast cancer treatment." (PMID 39015775, 2024). "As HGF activator inhibitors, serine protease inhibitor, Kunitz types 1 and 2 (SPINT1 and SPINT2) have been reported to be differentially expressed in breast cancer, but their prognostic significance and functioning mechanism remain unclear." (PMID 34381422, 2021). "The Linkedomics results showed that SPINT1 and SPINT2 were reciprocally correlated in breast cancer (Pearson correlation = 0.437, P = 2.103e−52), which was close to the correlation statistics from cBioportal (TCGA, Firehose Legacy) (Pearson correlation = 0.42, P = 4.68e−83)." (PMID 34381422, 2021). "The results showed that higher expression of SPINT1 was correlated with poorer OS (HR = 1.53, 95% CI = 1.22–1.92, P = 0.00019), RFS (HR = 1.21, 95% CI = 1.07–1.37, P = 0.002), and DMFS (HR = 1.42, 95% CI = 1.15–1.74, P = 0.00094) in breast cancer patients." (PMID 34381422, 2021). "SPINT1, which is one of the Kunitz-type serine protease inhibitors and also known as HAI-1, can inhibit hepatocyte growth factor function via regulation of HGFA, matriptase, and hepsin to inhibit the migration, proliferation, and invasion of breast cancer, indicating a good prognosis." (PMID 33336077, 2021). "Notably, multiple sex-biased switch-like genes—including SPINT1 and SPINT234, multiple keratin genes 35, and the oxytocin receptor gene 36,37 (OXTR)—in the breast tissue are differentially expressed in breast cancers relative to matched non-cancerous tissues." (PMID 39315271, 2024). "Survival of breast cancer patients with high ST14/Prss14 expression is significantly poor in estrogen receptor (ER) negative populations regardless of the ratios of ST14/Prss14 to its inhibitors, SPINT1 or SPINT2." (PMID 27167193, 2016).
prostate carcinoma (10 papers, 2011 to 2025). A carcinoma that arises from epithelial cells of the prostate gland. "Accordingly, SPINT1 attenuation in prostate cancer cell lines, resulted in a more aggressive phenotype which included enhanced motility and invasiveness." (PMID 21747944, 2011). "Collectively these data suggest that SPINT1 acts as a tumor suppressor in Prostate cancer." (PMID 21747944, 2011). "Recently, in a study which compared tissues and cell lines representing different stages of Prostate cancer, Spint1 was highly expressed in normal tissues compared with Benign Prostatic Hyperplasia (BPH) and low-grade cancer, with a progressive loss in increasing tumor grade specimens." (PMID 21747944, 2011).
colorectal cancer (8 papers, 2006 to 2024). A primary or metastatic malignant neoplasm that affects the colon or rectum. "Further, SPINT1 gene expression and methylation (average across all SPINT1-associated methylation probes) correlation analysis revealed a weak but positive correlation in colorectal cancer samples." (PMID 38212428, 2024). "Serine protease inhibitor, kunitz-type, 1 (SPINT1) is a type II transmembrane serine protease inhibitor that has been shown to be involved in the development of several types of cancer, such as squamous cell carcinoma and colorectal cancer." (PMID 31519199, 2019). "However, whether dysregulated CDX2 levels correlate with ST14 and SPINT1 in clinical colorectal cancer specimen needs to be clarified." (PMID 30087389, 2018). "Kunitz-type protease inhibitor 1 (SPINT1), a type II transmembrane serine protease inhibitor, has been shown to be involved in the development of several types of cancer, such as squamous cell carcinoma and colorectal cancer." (PMID 32602849, 2020).
intestinal tumor (6 papers, 2014 to 2024). "Strikingly, pharmacological inhibition of NF-κB activation reduces the formation of intestinal tumors in Spint1-deficient ApcMin/+ mice, unequivocally demonstrating that Spint1-driven inflammation promotes tumorigenesis." (PMID 31519199, 2019). "We have previously reported that the intestine-specific Spint1-deleted ApcMin/+ mice showed accelerated formation of intestinal tumors." (PMID 27612426, 2016). "In addition, intestine-specific Spint1 deletion in mice induces the activation of the master inflammation transcription factor NF-κB and accelerated intestinal tumor formation." (PMID 31519199, 2019). "Interestingly, even in mice carrying the wild-type Spint1 gene, intestinal tumor cells in ApcMin/+ mice showed significantly decreased HAI-1 immunoreactivity on the cell surface." (PMID 25268161, 2014).
pancreatic cancer (6 papers, 2010 to 2025). "Similarly, loss of SPINT1 in human pancreatic cancer cells promotes ST14-dependent metastasis in nude mouse orthotopic xenograft models." (PMID 31519199, 2019). "Finally, SPINT1 knockdown in the pancreatic cancer cell line SUIT-2, induced EMT and invasion which were accompanied by ZEB2 elevation and CDH1 reduction." (PMID 21747944, 2011).
colon carcinoma (5 papers, 2014 to 2019). "Our observation that induced CDX2 expression in LS174T cells promotes an increased ST14/SPINT1 ratio does not correlate with the reported expression pattern of decreased CDX2 levels and increased ST14/SPINT1 levels during colon cancer progression." (PMID 30087389, 2018).
gastric cancer (5 papers, 2018 to 2023). A primary or metastatic malignant neoplasm involving the stomach. "Among the gastric cancer patients, all the 15 overlapping genes appear to be isolated from each other, whereas among the controls, three gene pairs (SPINT1 and GMDS, GMDS and TNRC18, and CSNK1D and RNF19B) are connected." (PMID 33596182, 2021). "Subsequent molecular analysis of clinical gastric cancer tissue samples further verified the negative correlation between MACC1 and SPINT1." (PMID 33751856, 2021).
lung carcinoma (5 papers, 2015 to 2021). "Intrigued by these observations, we extended the analysis to HGFAC and SPINT1; note, these were up-regulated in murine lung cancer tissues and are potential c-Myc target genes." (PMID 29254206, 2017). "Hepatocyte growth factor (HGF) is a known driver of both lung cancer pathobiology as well as M2 polarization, and its signaling is antagonized by the tumor suppressor gene HAI-1 (SPINT1)." (PMID 34185790, 2021).
placental insufficiency (5 papers, 2020 to 2023). Failure of the placenta to deliver an adequate supply of nutrients and oxygen to the fetus. "We next sought to validate the association between low circulating SPINT1 concentrations and placental insufficiency in an independent cohort." (PMID 32415092, 2020). "Here the authors demonstrate that low levels of circulating SPINT1 are associated to low birthweight, and several ultrasound and neonatal anthropomorphic indicators of placental insufficiency." (PMID 32415092, 2020). "We next investigated the association between SPINT1 and various clinical parameters of placental insufficiency." (PMID 32415092, 2020). "We validate the association between low circulating SPINT1 and placental insufficiency in two other cohorts." (PMID 32415092, 2020). "By screening proteins that are highly expressed on the surface of the placenta we have identified a strong association between low circulating concentrations of SPINT1 at 36 weeks’ gestation and placental insufficiency." (PMID 32415092, 2020). "Importantly, in addition to being reduced in the maternal circulation, our prior report demonstrated that reduced circulating SPINT1 is associated with key indicators of placental insufficiency." (PMID 35207174, 2022). "Knockdown of NR4A2 under hypoxia significantly increased expression of NLR family pyrin domain containing 3 (NLRP3), a master regulator of the inflammasome (p = 0.0065) and Serine Peptidase Inhibitor, Kunitz Type 1 (SPINT1), associated with placental insufficiency (p = 0.0056)." (PMID 34667209, 2021). "Thus, we validated that circulating SPINT1 concentrations are correlated with several clinical parameters that are associated with placental insufficiency in a high-risk cohort from a different country than the cohort we used to discover the association." (PMID 32415092, 2020). "Our study suggests circulating SPINT1 around 36 weeks’ gestation may have a considerably stronger association with several indicators of placental insufficiency than PIGF." (PMID 32415092, 2020). "Now we have made the primary observation that low SPINT1 is associated with placental insufficiency, it may be worthwhile for future studies to elucidate molecular mechanisms and to tease out whether it is a bystander, or driver of placental disease." (PMID 32415092, 2020). "Low circulating SPINT1 is a marker of placental insufficiency and may identify pregnancies with an elevated risk of stillbirth." (PMID 32415092, 2020). "Thus, we examined the association between SPINT1 and many indicators of placental insufficiency." (PMID 32415092, 2020). "In the search for biomarkers for placental insufficiency, we identified SPINT1 as a promising candidate." (PMID 35207174, 2022). "This study demonstrates that SPINT1 levels are decreased in preterm pregnancies with placental insufficiency manifesting as FGR, even in the presence of concurrent preeclampsia." (PMID 35207174, 2022). "By screening 22 proteins in cohort 1 we identify a strong association between low circulating plasma serine peptidase inhibitor, Kunitz type-1 (SPINT1) concentrations and low birthweight (<10th centile), a marker of placental insufficiency in utero." (PMID 32415092, 2020). "Here we show a strong association between low circulating plasma serine peptidase inhibitor Kunitz type-1 (SPINT1) concentrations at 36 weeks’ gestation and low birthweight, an indicator of placental insufficiency." (PMID 32415092, 2020). "We also show SPINT1 expression is decreased in placentas from cases of preterm fetal growth restriction (a severe form of placental insufficiency) and from an animal model of fetal growth restriction." (PMID 32415092, 2020). "Furthermore, combining SPINT1 with other biomarkers (including those that are yet to be reported) or with ultrasound findings at different gestations may yield a highly accurate diagnostic test of fetal growth restriction and placental insufficiency." (PMID 32415092, 2020).